ALK (ALK receptor tyrosine kinase)
Diseases named in the same sentence as ALK in open-access papers (continued):
Sharing a sentence is not in itself a finding about the gene and the disease.
tumor (continued). "To start addressing this issue, we developed a spatial ABM of tumor tissue, reflecting therapeutic responses of a xenograft model of ALK+ NSCLC." (PMID 39001467, 2024). "It would e.g. be of interest to examine PRRT combined with ALK TKI, in order to study how inhibition of the ALK signaling pathway affects the anti-tumor effects following radiation." (PMID 38826727, 2024). "Many common cancers have ALK overdrive as one part of their suite of growth driving elements, thus making pharmacological or other ALK inhibition a potential “tumor agnostic target”." (PMID 39056757, 2024). "Anaplastic lymphoma kinase (ALK) is a transmembrane receptor tyrosine kinase that is highly expressed in various tumor cells." (PMID 39451714, 2024). "To further investigate how WNT and periostin influenced each other, we first treated ALK/MYCN tumor cells with the WNT inhibitor WNT-C59 at 10 μM for 48 h." (PMID 38451815, 2024). "Switching to lorlatinib allowed for the continuation of ALK inhibitor therapy and successful tumor reduction." (PMID 39527462, 2024). "There are frequent genomic alterations in these neoplasms, especially in the mitogen-activated protein kinase pathway, including BRAF (notably BRAF V600E), MAP2K1, KRAS, and NRAS mutations, and ALK gene translocation." (PMID 38713245, 2024). "Tall column‐shaped tumour cells were negative or weakly positive for thyroid transcription factor‐1 (TTF‐1) and strongly positive for ALK mutation, whereas quasi‐circular tumour cells were positive for TTF‐1 and less positive for ALK mutation." (PMID 38616354, 2024). "The direct involvement of CD147 with glycolysis was demonstrated through the CD147 knockdown in ALK+ ALCL cells, which led to the loss of MCT1 expression, reduction in glucose consumption, and retardation of tumor growth." (PMID 39273126, 2024). "The patient received multiple pirarubicin-based chemotherapy treatments and an ALK inhibitor (anlotinib) within 6 months after surgery, but the tumor recurred." (PMID 38968455, 2024). "A liquid biopsy provides a depiction of circulating tumor DNA (ctDNA) present in the blood, which can help guide the selection of initial ALK TKI and subsequent lines of therapy upon progression." (PMID 38835344, 2024). "The tumor in the third patient expressed ALK-WT and progressed after therapy with alectinib, prompting a switch to lorlatininb." (PMID 38168093, 2024). "Targeted therapeutic approaches, including ALK inhibitors and anti-GD2 immunotherapy, have shown promising efficacy in improving clinical outcomes by addressing specific genetic mutations driving tumor growth." (PMID 39458991, 2024). "ein inflammatorischer myofibroblastärer Tumor (ebenfalls ALK+, jedoch sm-Aktin+), differentialdiagnostisch in Betracht kommen, zumal die Histomorphologie der ALK-positiven Histiozytose oft ein solides, wirbeliges Wuchsmuster von Spindelzellen zeigt." (PMID 38602523, 2024). "Pathologists should be aware of this entity, particularly as it is challenging to differentiate from other more frequent neoplasms of the same disease group or mesenchymal neoplasm with ALK aberration." (PMID 38602523, 2024). "ALK supports tumor development by promoting cell proliferation, differentiation, survival, inhibiting apoptosis, enhancing cell invasion and metastasis, and stimulating angiogenesis." (PMID 39451714, 2024). "Gold nanoparticles have been developed for multi-headed PROTACs aimed at treating NSCLC, demonstrating superior ALK degradation and tumor-specific accumulation compared to traditional dual-functional PROTACs." (PMID 39500878, 2024). "Reciprocally, inhibition of the WNT pathway reduced expression of POSTN and growth of ALK/MYCN tumor cells." (PMID 38451815, 2024). "APG-2449, a TKI targeting ALK, ROS1, and focal adhesion kinase (FAK), has shown anti-tumor activity in preclinical models and is currently being tested in a phase I dose escalation and expansion trial that enrolled patients with ALK/ROS1 positive NSCLC." (PMID 39199633, 2024).
tumor (continued). "This trial specifically focused on patients with PD-L1 expression levels of ≥1% on tumor cells or immune cells, excluding those with EGFR mutations or ALK translocations." (PMID 39199653, 2024). "After that, her specimen was reviewed, showing that the tumor originated from B cells, which was consistent with ALK+ LBCL." (PMID 39906668, 2024). "The main limitation of the current scoping review derives from the scarce evidence available in the literature regarding ALK in tumors of the posterior fossa, mostly in the form of case reports." (PMID 38339401, 2024). "We performed next-generation sequencing on a cohort of 46 pediatric ALK+ ALCLs, including 42 tumor samples obtained at diagnosis and four relapsed samples (1 patient with paired diagnostic-relapsed samples)." (PMID 38585847, 2024). "In this context, it would also be interesting to perform retrospective analyses of tumor samples before and after lorlatinib treatment, which would allow to check if ALK expression increased." (PMID 38688910, 2024). "In the present study we aimed to identify tumor markers specific for ALK‐positive NSCLC by comparing tumor marker levels between patients with ALK‐positive and EGFR‐positive NSCLC." (PMID 38400801, 2024). "JUNB is a member of the AP-1 transcription factors, and has been shown in previous studies to regulate tumor growth and proliferation in ALK+ALCL 50–53." (PMID 38585847, 2024). "The waterfall plot similarly showed a strong trend between PDC AUC values and the clinical tumor response to EGFR- or ALK-TKIs." (PMID 38398169, 2024). "This combination is now FDA-approved for treating metastatic or recurrent NSCLC as a first-line treatment, excluding those with EGFR or ALK genomic tumor aberrations." (PMID 39410008, 2024). "Meanwhile, ALK release into the tumor microenvironment stimulates tumor-associated macrophages (TAM) and B-cells, shaping a milieu conducive to tumor growth and immune evasion." (PMID 38397899, 2024). "ALK rearrangement was identified from the onset of the tumor’s history by immunochemistry and confirmed later on molecular genomic analysis." (PMID 39931211, 2024). "This activation of ALK signaling in the tumor cells is brought about by mechanisms such as gene fusions, chromosomal translocations, gene amplification or deregulation, and activating point mutations." (PMID 38474400, 2024). "In the context of ALK+ NSCLC models, the ALK-DNA vaccine triggered robust immune responses, curtailing tumor growth and elongating survival." (PMID 38397899, 2024). "ALK gene fusion was demonstrated by counting at least 100 cells and observing a positive signal (segregating and/or segregating 3’signals) in 15% of the tumor cells." (PMID 39867882, 2024). "The R1275Q mutation in ALK was also identified as a therapeutic target for crizotinib, lorlatinib, and TAE684 in one of our tumor samples, although this mutation was likely to exhibit resistance to TAE684." (PMID 39338204, 2024). "Further studies examining cfDNA as a prognostic biomarker and ALK+ tumor responses consistently favored alectinib over crizotinib." (PMID 38397899, 2024). "By comparison, only ALK (+) ALCL cells have high expression of MCT1 on the tumor cell membrane and widespread expression of MCT4." (PMID 39464313, 2024). "The presence of IR-780 in the probe enabled NIR fluorescence emission, while Crizotinib’s specific binding to ALK inhibited relevant signaling pathways, resulting in reduced tumor cell growth and proliferation." (PMID 39451714, 2024). "In such cases, treatment with ALK-targeting drugs, such as crizotinib and alectinib, can lead to durable tumor responses." (PMID 39906487, 2024). "Nevertheless, tumor progression was detected, and a liver biopsy was recommended, considering the possibility of ALK inhibitor resistance." (PMID 38740834, 2024). "The goal of adding chemotherapy following treatment with ALK TKI is to target TKI-resistant tumor cells." (PMID 38835344, 2024).
tumor (continued). "Understanding these dynamics is pivotal in developing targeted therapies against ALK-driven tumors, aiming to recalibrate the immune landscape and disrupt tumor-promoting interactions." (PMID 38397899, 2024). "The limited availability of ALK IHC in previously reported cases makes it difficult to draw definitive conclusions regarding the association between ALK1 status and tumor recurrence in laryngeal IMT." (PMID 39171208, 2024). "Another work describes a method for detecting ALK fusions in circulating plasma tumor RNA by measuring the difference in expression of the exon 20/exon 3 portion using qPCR." (PMID 39594806, 2024). "Another novel ALK TKI is NVL-655, a highly CNS penetrant TKI with activity against some of the common compound mutations seen in lorlatinib resistant tumours." (PMID 38347643, 2024). "The tumor demonstrated a novel THBS1::ALK fusion containing Exons 1–7 of the thrombospondin 1 (THBS1) gene fused to Exon 19 of the anaplastic lymphoma kinase (ALK) gene via next-generation sequencing with the NextSeq sequencer." (PMID 39171208, 2024). "Tumor cells showed widespread membrane positivity for ALK-IHC with positive expression of transcription factor E3 (TFE3)-IHC." (PMID 39205743, 2024). "Further, preclinical studies indicate that dual MEK and ALK inhibition effectively suppresses tumor growth, highlighting the potential for combination therapies to overcome pathway-specific resistances." (PMID 39682234, 2024). "Preclinical studies demonstrated brigatinib’s potent activity against a range of ALK-positive tumor models, highlighting its potential pharmacodynamic benefits." (PMID 38611728, 2024). "Combination of selpercatinib with the dual NTRK/ALK inhibitor entrectinib reduced the tumor burden, which was followed by appearance of NTRK3 solvent-front G623R mutation." (PMID 38438731, 2024). "The most common off-target bypass signalling, detected in sotorasib and adagrasib resistant tumours, includes MET amplification, BRAF, NRAS, MAP2K1 mutations and RET, ALK, BRAF, FGFR and RAF1 fusions." (PMID 38347643, 2024). "ALK + tumors have an immunosuppressive tumor microenvironment which activates the PI3K-AKT and MEK-ERK pathways, leading to decreased responsiveness to ICIs." (PMID 38339280, 2024). "ALK-TKIs suppressed tumor growth and indirectly bolstered antitumor immunity by reducing PD-L1 expression." (PMID 38397899, 2024). "MET amplification was observed in 15% of tumor samples from patients progressing after second-generation ALK inhibitors, and in 12% and 22% of tumor biopsy samples from patients progressing on second-generation inhibitors or lorlatinib, respectively." (PMID 39055566, 2024). "Clinical studies demonstrate better outcomes in patients with ALK translocations confirmed by two independent methods as compared to subjects whose tumor was analyzed by a single IHC or FISH test." (PMID 38966170, 2024). "On the other hand, since ALK expression is restricted to tumor tissues with minimal expression in normal tissues, ALK is a potential target for NBL immunotherapy." (PMID 38804307, 2024). "ALK contributes to tumor growth by upregulating the extracellular matrix protein periostin and activating WNT signaling." (PMID 38451815, 2024). "Prognosis involves several factors such as age at diagnosis, tumor location, and genetic testing to identify NB-associated segmental chromosomal aberrations and mutations, especially in MYCN and Anaplastic Lymphoma Kinase (ALK)." (PMID 39101440, 2024). "These combination strategies enhance tumor response, prolong progression-free survival, and reduce resistance mechanisms, particularly in ALK-rearranged cancers." (PMID 39682234, 2024). "The patients described illustrate the potential of serum IL-6, IL-8 and IL-10 for tumour monitoring in ALK + NSCLC." (PMID 37120670, 2023).
tumor (continued). "First, it is well known that actionable mutations, such as epidermal growth factor receptor (EGFR) and anaplastic lymphoma kinase (ALK), lead to unregulated proliferation and survival of tumor cells and associated with advanced NSCLC stages." (PMID 36685035, 2023). "The tumor cells were positive for ALK, CD138, EMA, MUM-1, OCT2, Bob.1, and CD38 (partial) by immunohistochemistry." (PMID 37906510, 2023). "In a co-culture system of tumor cells and DC-cytokine-induced killer cells, PD-L1 expression in NSCLC cell lines was associated with EGFR mutations and ALK fusion genes, and ALK fusion protein overexpression increased PD-L1 expression." (PMID 37901223, 2023). "These drugs work by inhibiting the activity of abnormal ALK proteins, leading to tumor shrinkage and improved survival." (PMID 37993887, 2023). "Targeted therapy for metastatic lung cancer has been in routine use since pivotal studies showed high response rates and durable responses in individuals with tumours harbouring specific mutations, first related to aberrations in the EGFR and ALK genes." (PMID 36900294, 2023). "EGFR is closely linked to the progression of tumor resistance mechanisms when using anti-cancer medication, accompanied by the marked induction of specific point mutations in EGFR and ALK rearrangements." (PMID 37155147, 2023). "The source of tumor tissue used for ALK gene sequencing was variable, with some from tumor obtained before relapse and others from tissue biopsies performed at relapse yet not at time of enrollment." (PMID 37012551, 2023). "The same ALK expression patterns were observed in the cytoplasm of tumor tissues from patients positive with ALK rearrangement." (PMID 37993887, 2023). "Detection of ALK rearrangement and/or expression of the ALK protein is an essential component in the evaluation of many neoplasms." (PMID 38175372, 2023). "mRNA expression of Met and ALK was significantly elevated in patient tissue and tumor cells isolated from primary tissue compared to their respective normal margins; however, ROS1 expression was barely detectable in both tumor samples and resected margins." (PMID 38144528, 2023). "Our previous study revealed that large‐sized tumour cells expressed ten‐fold more NPM‐ALK mRNA transcripts than small‐sized tumour cells, indicating that large‐sized tumour cells acquiring L1196M ALK mutation can survive alectinib administration." (PMID 36819147, 2023). "Unfortunately, nearly one third of the patients bearing an ALK rearrangement and receiving crizotinib develop CNS metastases within one year of therapy sometimes as the only extra-thoracic site of tumor progression." (PMID 36786970, 2023). "This dynamic event highlights the importance of tumor re-biopsy and repeated ALK state evaluation during disease progression." (PMID 36765519, 2023). "Immunotherapy is considered the standard approach for most patients with newly diagnosed EGFR-WT/ALK-WT mNSCLC and tumour PD-L1 ≥ 50%." (PMID 37386452, 2023). "Three patients had additional ALK alterations detected by ctDNA at baseline along with the identified tumor ALK alteration, two of whom had received a prior ALK TKI." (PMID 37012551, 2023). "The Negr1-derived peptide described here demonstrated the capability to degrade ALK and slow tumor progression in vitro and in vivo." (PMID 37765276, 2023). "This PNET was determined to have high levels of ALK protein overexpression in the limited tumor sample, which led to utilizing targeted therapy with crizotinib on a palliative basis." (PMID 36619485, 2023). "Most ALK-rearranged NSCLC with high tumour PD-L1 expression (TPS ≥ 50%) seems to lack high levels of TILs." (PMID 37371571, 2023). "It has been reported that EGFR mutations and ALK rearrangements play a significant role in the invasion of circulating tumor cells through the blood–brain barrier (BBB) and tumor angiogenesis, resulting in BM in NSCLC patients." (PMID 37573417, 2023).
tumor (continued). "The common type of ALK-positive ALCL is characterized by large tumor cells with horseshoe-shaped nuclei, abundant cytoplasm containing numerous vacuoles, and strong positive staining for ALK and CD30." (PMID 38136278, 2023). "The MPR and pCR rates increased to 41.2% (7/17; 95% CI 18.4–67.1%) and 23.5% (4/17; 95% CI 6.8–49.9%), respectively, when patients with known tumor EGFR mutations and ALK rearrangements (EGFR/ALK alterations) were excluded in the Nivo+CT arm." (PMID 36928818, 2023). "Standard assessment of tumor tissue includes rapid testing for EGFR mutations, ALK fusions and ROS1 fusions." (PMID 37948122, 2023). "They found that the possible mechanism of ALK TKI resistance is the evolution of high tumor mutation burden (TMB) and tumor heterogeneity." (PMID 36911198, 2023). "Among the cytokines tested, the most significant indicators of tumour progression in ALK + NSCLC were IL-6, IL-8 and IL-10." (PMID 37120670, 2023). "Here, we performed multiregional characterization of an aggressive chemoresistant ALK‐rearranged lung tumor and corresponding tumor‐derived cultures." (PMID 36423211, 2023). "The results showed that VAF of some mutations in tumor tissues are significantly higher than those in plasma, e.g. EGFR p.Leu858Arg, KRAS p.Gly12Cys and ALK." (PMID 37004022, 2023). "Extracellular vesicles were isolated from the blood of 28 additional NSCLC patients with tumor biopsies positive for ALK rearrangements (n = 26), RET rearrangements (n = 1), or MET∆ex14 (n = 1) by NGS, FISH, IHC, or qPCR." (PMID 37243883, 2023). "Current data suggests that ALK inhibitors have tissue-agnostic activity in neoplasms bearing ALK fusions/rearrangements." (PMID 37773318, 2023). "As a potential resistance mechanism, P-gp overexpression was determined in patients with tumor tissues of crizotinib- and ceritinib-resistant ALK mutant NSCLC." (PMID 36768562, 2023). "Here, we investigated the utility of circulating cytokines, which are easily accessible serum analytes, for tumour monitoring in ALK + NSCLC, and evaluated the orthogonal merit of cytokine analysis to ctDNA in a multi-analyte liquid biopsy approach." (PMID 37120670, 2023). "This case demonstrates the clear benefit of targeted therapy in salvage scenarios as a sustained response was produced given the dependence of our patient's tumor on ALK‐pathway signaling." (PMID 36619485, 2023). "ALK expression patterns were observed in the cytoplasm of tumor tissues and PDOs from all 6 patients positive for ALK rearrangement." (PMID 37993887, 2023). "A clonal nonsense driver mutation in SETD2 was lost at relapse, and several subclonal variants were observed in ALK and MYCN in <5% of the tumor cells, which is often observed in highly amplified oncogenes." (PMID 36867694, 2023). "There were no notable differences in the median percentage of residual viable tumor in resected tumors harboring EGFR/ALK alterations compared with wild type." (PMID 36928818, 2023). "Consistently, our in vivo data indicated that combination therapy with ALK-TKIs and panitumumab inhibited the development of tumor recurrence following treatment termination." (PMID 37917191, 2023). "In murine ALK-mutant xenografts, tumor growth was likewise reduced or delayed, and survival was prolonged upon combinatorial treatment of TNO155 and lorlatinib." (PMID 38032104, 2023). "We have previously established the utility of ctDNA detection for tumour monitoring in ALK + NSCLC using targeted panel and shallow whole genome sequencing-based assays." (PMID 37120670, 2023). "It recognizes the tumor agnostic potential of ALK rearrangements in cancer, which have shown to respond to ALK-directed therapies outside of non-small cell lung cancer." (PMID 37041305, 2023).